KIT (KIT proto-oncogene, receptor tyrosine kinase)
Diseases named in the same sentence as KIT in open-access papers (continued):
Sharing a sentence is not in itself a finding about the gene and the disease.
metastatic melanoma (50 papers, 2008 to 2024). A melanoma that has spread from its primary site to another anatomic site. "For patients with resistant c-KIT mutation, a second-generation tyrosine kinase inhibitor such as nilotinib was proven more efficient than imatinib in GISTs and metastatic melanoma." (PMID 35720122, 2022). "The combination of pembrolizumab and imatinib was reported in the case of a patient with a metastatic melanoma and double KIT mutations (V559 and N822I)." (PMID 34831002, 2021). "These drugs have been used clinically and can significantly extend the lifespan of patients with metastatic melanoma carrying KIT mutations." (PMID 32894090, 2020). "Nilotinib is a small molecule that showed activity among KIT mutated advanced or metastatic melanoma patients in four clinical studies." (PMID 32850962, 2020). "We report a case of an 82-year-old female with metastatic melanoma who was found to have double KIT mutations at V559 and N822I." (PMID 31689840, 2019). "Baseline and 4-week follow-up 18F-FDG-PET/CT were evaluated in 17 patients with metastatic melanoma and KIT amplifications and/or mutations treated with imatinib in a multicenter phase II clinical trial." (PMID 25609545, 2014). "Thereby, c-KIT has been implicated in the pathogenesis of several cancers including metastatic melanoma, and previous clinical trials demonstrated a durable overall RR (16–24%) as well as a median OS ranging from 11 to 14 months." (PMID 23533766, 2013). "The phase II trial, in 46 metastatic melanoma patients with c-KIT mutations or amplifications, demonstrated an overall response rate of 23.3%." (PMID 23515890, 2013). "Recent phase II clinical trials involving patients with metastatic melanoma harbouring KIT mutations reported significant clinical responses to imatinib in a subset of patients." (PMID 22281663, 2012). "Based on these data, imatinib has shown promising results as a therapeutic agent in metastatic melanoma patients with c-KIT mutations." (PMID 22333219, 2012). "The observed clinical responses support further investigation of KIT inhibitors in metastatic melanoma, selected according to KIT mutation status." (PMID 20372153, 2010). "In 2016, a clinical trial was set up in order to evaluate the clinical benefit of combining pembrolizumab and imatinib in patients with locally advanced/metastatic melanoma harboring c-KIT Mutation/Amplification (NCT02812693), but unfortunately, the trial was withdrawn due to poor accrual." (PMID 33918490, 2021). "KIT was initially thought to act as a tumor suppressor gene, because its presence in normal melanocytes and benign nevi, and its loss during progression and in metastatic melanoma was reported." (PMID 32850962, 2020). "Combining Imatinib with checkpoint inhibitors may be efficacious in patients with metastatic melanoma and KIT mutations." (PMID 31689840, 2019). "In patients with metastatic melanoma and KIT amplifications and/or mutations, therapy with imatinib mesylate may prolong survival." (PMID 25609545, 2014). "The KIT inhibitor imatinib has shown efficacy in providing a durable response in patients with KIT mutant metastatic melanoma, with a subset of patients showing a complete response of more than 1.5 years." (PMID 39199633, 2024). "So, inhibiting mutant-like KIT in metastatic melanoma with nilotinib and dasatinib is becoming increasingly popular." (PMID 35889263, 2022). "A phase I clinical trial explored the efficacy of the KIT inhibitor dasatinib with the alkylating agent dacarbazine in the treatment of metastatic melanoma." (PMID 35954441, 2022). "c-KIT-targeted therapies enabled the single or combined treatments by receptor tyrosine kinase inhibitors such as imatinib or sunitinib in primary or metastatic melanoma patients." (PMID 35720122, 2022).
metastatic melanoma (continued). "In a case report published in 2019, imatinib, a KIT inhibitor, was combined with pembrolizumab, a PD-1 inhibitor, in a patient with metastatic melanoma with double-mutant KIT receptor." (PMID 35954441, 2022). "The results of independence testing analysis showed that genes of CXCL8 and THBS1 had a significant increase of gene expression in metastatic melanoma, but a significant downregulation of KIT expression." (PMID 32894090, 2020). "Treatment of metastatic melanoma targeting genetically activated oncogene pathways (BRAF/NRAS/KIT pathways) and so-called immune-checkpoints have significantly improved overall survival rates of metastatic melanoma patients in recent years." (PMID 29614062, 2018). "CfDNA is an essential source of material for management of metastatic melanoma patients as it allows detection of somatic targeting mutations (BRAF, KIT), copy number variations and the tumor mutation load." (PMID 30546839, 2018). "In summary, we describe the first report of metastatic melanoma of the esophagus arising in a background of BE with molecular analysis for the presence of BRAF and KIT mutations." (PMID 24220097, 2013). "Another clinical trial (NCT01099514) will also be investigating Nilotinib in metastatic melanoma with KIT aberrations." (PMID 23515890, 2013). "Of note, KIT levels are reported to be lower in metastatic melanoma cell lines than in benign nevi, and forced expression of KIT in these cells has been shown to induce apoptosis." (PMID 20862309, 2010). "Considering that the effective therapies were lacking and the outcome was routinely poor for metastatic melanoma, determination of the c-KIT mutation status was an alternative to the treatment." (PMID 35720122, 2022). "In addition, pazopanib, a multi-kinase inhibitor of VEGFR-1, 2, and 3, PDGFR, and c-KIT, is being combined with paclitaxel to treat patients with metastatic melanoma." (PMID 35954441, 2022). "For example, a rare activating BRAF mutation (p.L597R) was identified in an aggressive metastatic melanoma using whole genome sequencing that had previously been designated as “wild-type” for BRAF p.V600E/K mutations and several common KIT mutations using targeted sequencing." (PMID 27245685, 2016). "Eventually, rational combination of B-RAF inhibitors (e.g., vemurafenib, dabrafenib) with drugs that specifically target one of the molecules (e.g., MEK, c-KIT, or CTLA-4) would further improve the clinical outcome of the patients with advanced/metastatic melanoma." (PMID 23533766, 2013). "This is illustrated by the report of three patients with metastatic melanoma and strong immunohistochemical c-KIT expression who did not respond to a therapy with the c-KIT blocker imatinib." (PMID 19018266, 2008). "Most importantly, the absence of documentation of the examined molecular markers, such as BRAF, c-KIT, and CDK1, should not disorient readers from the importance of immunotherapeutic agents in metastatic melanoma." (PMID 39553047, 2024).
thymic carcinoma (47 papers, 2013 to 2026). Thymic carcinoma (TC) is a type of thymic epithelial neoplasm characterized by a high malignant potential. "Overexpression of c-KIT is observed in 50–88% of thymic carcinomas but is rare in thymomas (2–5%) and is linked to poor prognosis." (PMID 41300989, 2025). "Mutations in c-KIT were generally seen in approximately 9% of thymic carcinoma cases based on the The Cancer Genome Atlas Program analysis." (PMID 38254905, 2024). "KIT mutations are implicated in the pathogenesis of thymic carcinoma, and as such, CD117 positivity is found in approximately 80% of cases of thymic carcinoma and not found in other subtypes of thymoma." (PMID 39574984, 2024). "A case report of a thymic carcinoma patient who harbored an activating KIT mutation noted a clinical and radiographic response to imatinib therapy." (PMID 38254905, 2024). "A trend for the absence of co-occurrence with GTF2I was observed also for CDKN2A, BAP1, CYLD, and KIT mutations, which are genes frequently mutated in B3 thymomas and thymic carcinomas." (PMID 37671056, 2023). "Thymic carcinomas harboring KIT mutations have been documented to display sensitivity to targeted therapeutics such as imatinib." (PMID 37849766, 2023). "Of interest, KIT mutations, found in up to 11% of thymic carcinomas, represent one of the few targetable mutations in TETs." (PMID 36836670, 2023). "In this study, frequently mutated genes in thymic carcinomas included KIT, DDR2, PDGFRA, ROS1, and IGF1R." (PMID 35884448, 2022). "In CUP-03 we detected a KIT p.V560D mutation and transcriptomic profiling matched with thymic carcinomas." (PMID 35918329, 2022). "Mutation of the tyrosine kinase KIT was the only known targetable alteration in thymic carcinoma, but it is present in only 6–12 % of cases." (PMID 27844328, 2017). "KIT mutation is rare in thymic carcinoma, but so far the only known molecular target based on few, but encouraging case reports." (PMID 27844328, 2017). "Another study, which analyzed 48 cases of thymic carcinoma, identified only six that contained KIT gene mutations: Four within exon 11 (V559A, L576P, Y553 N, W557R), one within exon 9 (E490 K) and one within exon 17 (D820E)." (PMID 25789028, 2015). "So far, only few cases of metastasizing thymic carcinoma with an activating KIT mutation and a partial response to treatment with Imatinib have been described." (PMID 24934485, 2014). "KIT mutations are uncommon in thymic carcinoma; however, retrospective studies have shown that KIT-mutated thymic carcinoma has a meaningful clinical response to imatinib, although the association between KIT expression and response to Sunitinib and Sorafenib is uncertain." (PMID 41300989, 2025). "Finally, we detected a pathogenic KIT p.(Leu576Pro) variant in 1 of 34 (3%) thymic carcinomas; this frequency is similar to previous studies." (PMID 35884448, 2022). "Therefore, KIT is considered the classical diagnostic marker for thymic carcinoma, and the efficacy of targeted therapy for KIT has been reported." (PMID 34680386, 2021). "CD117 is expressed in about 86% of thymic carcinomas, but KIT gene mutations are uncommon." (PMID 24934485, 2014). "Several subsequent studies evaluated the IHC expression of c-KIT in thymic neoplasms, revealing positivity in 4% of thymomas and 80–86% of thymic carcinoma cases." (PMID 38254905, 2024).
thymic carcinoma (continued). "On the contrary, mutations in tyrosine kinase receptors and other oncogenes are only occasional, with those of KIT being the most common and present in only 10% of thymic carcinomas." (PMID 38201593, 2023). "An analysis of the mutational status of druggable targets such as EGFR, c-KIT, KRAS, BRAF, PDGFR, HER2, and c-MET in thymic epithelial tumors did not reveal any targetable mutations except infrequent c-KIT mutations in thymic carcinoma." (PMID 36612283, 2022). "In thymic epithelial tumors, KIT expression is seen in 73–86% of thymic carcinomas, while its expression is ˂5% in thymoma." (PMID 34680386, 2021). "Immunohistochemical staining for PAX8, CD5, c-KIT, TdT, and CD1a also demonstrated features that are characteristic to thymic carcinoma." (PMID 34328560, 2021). "In KIT mutant thymic carcinoma exon 9/c490, exon 11/c553, c557, c559, c576 confers sensitivity, while exon 17/c820 mutation caused resistance to KIT inhitors." (PMID 31848942, 2020). "Although data on the correlation between genetic alterations and response to immunotherapy are available in the majority of common cancers, data are lacking in the subset of patients with KIT-mutated Thymic Carcinoma (TC)." (PMID 39996868, 2025). "Despite c-KIT expression being detected in a modest 0%-5% of thymomas and a substantial 50%-88% of thymic carcinomas, it does not consistently parallel the presence of KIT mutations." (PMID 37849766, 2023). "Even if GTF2I mutations are common in A and AB thymomas, there are no clinically relevant targets in TETs except for KIT mutations observed in only 10% of thymic carcinomas." (PMID 37671056, 2023). "The presence of KIT expression in normal medullary tuft cells and in thymic carcinomas appears to support this hypothesis." (PMID 38201593, 2023). "Druggable KIT alterations in thymic carcinomas have potential as therapeutic targets." (PMID 35884448, 2022). "Importantly, druggable KIT alterations in thymic carcinomas, such as KIT p.(Leu576Pro), have potential as therapeutic targets." (PMID 35884448, 2022). "However, immunohistochemical evaluation, including expression patterns of PAX8, CD5, c-KIT, TdT, and CD1a that are characteristic to thymic carcinoma, confirmed the diagnosis in our patient." (PMID 34328560, 2021). "In addition, SOX9 expression was positively associated with the expressions of TRPM5, which is required for the function of thymic tuft cells, and KIT, which is frequently expressed in thymic carcinomas." (PMID 34778027, 2021). "c-KIT expression has been demonstrated to be common in thymic carcinomas." (PMID 26735216, 2015). "For example, in a phase 2 study of sunitinib, a multi-targeted tyrosine kinase inhibitor of VEGFR, KIT, and PDGFR, there was notable activity in patients with thymic carcinoma, with a DCR of 91% and response rate of 26% in 23 evaluable patients." (PMID 34136086, 2021).
thymic carcinoma (continued). "On comparing thymoma and thymic carcinoma, EGFR overexpression was noted in 23% vs. 67–100%, HER2 overexpression in 6% vs. 53%, KIT overexpression in ˂5% vs. 73–86%, and BCL-2 overexpression in 14% vs. 100%, respectively." (PMID 34680386, 2021). "While drugs like imatinib, sunitinib, and other tyrosine kinase inhibitors with inhibitory activity against KIT have shown anecdotal responses in a few patients, phase II trials of imatinib in non-selected thymic carcinomas have yielded disappointing results." (PMID 38201593, 2023).
germ cell tumor (45 papers, 2004 to 2025). A benign or malignant, gonadal or extragonadal neoplasm that originates from germ cells. "This case underscores the clinical and genetic overlap between germ cell tumors and hematological malignancies in pediatric patients, highlighting the role of KIT mutations as a potential unifying driver." (PMID 41568380, 2025). "Although mutations in KIT are recognized as key drivers of clonal evolution in both germ cell tumor and hematological malignancies, the clinical and genomic interactions between GCT and SM remain largely unexplored, particularly in the pediatric population." (PMID 41568380, 2025). "D816 mutations in the KIT gene are common to germ cell tumors and we thus tested a biopsy specimen that was obtained from the dysgerminoma lesion in our study case prior to chemotherapy." (PMID 33246418, 2020). "KIT D816 mutations are also commonly observed in germ cell tumors, and have been found in one-third of ovarian dysgerminomas." (PMID 33246418, 2020). "Apart from these SNPs, other genetic alterations of the KIT/KITLG pathway have been linked to an increased susceptibility to testicular germ cell tumors." (PMID 28036409, 2016). "Mutations in the KIT gene at codon 816 are associated with gonadal and extragonadal germ cell tumours." (PMID 24286014, 2013). "Mutations in germ cell tumors have been found in both the juxtamembrane domain and the kinase domain of c-KIT, while mutations in GISTs tend to occur in exon 11 of the juxtamembrane domain of c-KIT." (PMID 16579858, 2006). "KIT has been shown to be expressed in some TGCT and somatic mutations in KIT have recently been identified in testicular and mediastinal germ cell tumours." (PMID 15150569, 2004). "The etiological linkage between ASM and a preceding germ cell tumor caused by a KIT D816 mutation is further supported by a similar prior report of an ASM patient carrying KIT D816V who had previously had an ovarian germ cell tumor harboring this same mutation." (PMID 33246418, 2020). "Notably, two independent GWAS found that allele variations in KITLG (the unique ligand for the receptor tyrosine kinase KIT) were the strongest genetic risk factors for testicular germ cell tumors." (PMID 28036409, 2016). "Previous studies have indicated that KIT mutations found in germ cell tumours are somatic." (PMID 15150569, 2004). "For the tested KIT mutations, only testicular germ cell tumors (TGCT) had enough mutated cases sufficient for our analysis." (PMID 30442178, 2018). "Immunostains showed expression of Sal‐like protein 4 (SALL4) and KIT (CD117) which are consistent with germ cell tumor." (PMID 34548993, 2021). "In this context pazopanib, a multitarget TKI against VEGFR 1–3, platelat derived growth factor (PDGFR) and c-KIT was used in a single-arm phase 2 study for patients with refractory germ cell tumors after at least failure of ≥2 platinum-based regimens." (PMID 29250197, 2017). "However, phase II trials of imatinib in unselected or KIT-positive germ cell tumors have shown limited efficacy, possibly due to activating mutations at the KIT kinase domain that confer resistance to blockade." (PMID 41018086, 2025). "Despite this heterogeneity, most germ cell tumors demonstrate common molecular alterations of the MAPK and/or AKT/mTOR pathways, with various degrees of mutations in the KIT gene, which ultimately inhibit programmed cell death of primordial germ cells in the CNS." (PMID 37519792, 2023). "Our findings of positive c-KIT expression in 27% of SEM from the necropsy group (50% of diffuse SEM, 14% of intratubular SEM) and 40% of biopsied SEM (45% of diffuse SEM, 0% of intratubular SEM) are consistent with literature reports, in which germ cell tumors can express c-KIT." (PMID 25096628, 2014). "However, a pathogenic missense KIT activating variant, previously not described in germ cell tumors, was discovered in the dysgerminoma of the 13-year-old girl." (PMID 37575996, 2023).